IL7R (interleukin 7 receptor)
Diseases named in the same sentence as IL7R in open-access papers (continued):
Sharing a sentence is not in itself a finding about the gene and the disease.
influenza (18 papers, 2010 to 2024). An acute viral infection of the respiratory tract, occurring in isolated cases, in epidemics, or in pandemics; it is caused by serologically different strains of viruses (influenzaviruses) designated A, B, and C, has a 3-day incubation period, and usually lasts for 3 to 10 days. "Using IL-7Rα signaling deficient mice, we show that IL-7 is required for a normal sized mediastinal lymph node and the early clonal expansion of influenza-specific CD8 T cells therein." (PMID 34997007, 2022). "To assess the importance of IL-7 signaling in CD8 T cells following infection with influenza, we used mice expressing a mutated IL-7Rα whereby a cytoplasmic tyrosine important for signal transduction is substituted to a phenylalanine at residue 449 (IL-7Rα449F)." (PMID 34997007, 2022). "In addition, loss of IL-7R and IL-15R expression is associated with the disappearance of memory T-cells in respiratory tract following influenza infection." (PMID 28096567, 2016). "MANA-specific T cells also express far less IL-7R relative to influenza TRM, translating functionally into poor IL-7 responsiveness." (PMID 34290408, 2021). "MANA-specific CD8 T cells have hallmark transcriptional programs of tissue-resident memory (TRM) cells, but low levels of interleukin-7 receptor (IL-7R) and are functionally less responsive to interleukin-7 (IL-7) compared with influenza-specific TRM cells." (PMID 34290408, 2021). "Indeed, IL-7R expression was 4.6-fold higher on influenza-specific TIL relative to MANA-specific TIL." (PMID 34290408, 2021). "Importantly, antigen-specific IL-6Rα+IL-7R+ CD4+ T cells emerge from the effector population at late time points post influenza infection." (PMID 26743592, 2016). "Importantly, at late time points post influenza infection, a population of antigen-specific IL-6Rα+IL-7R+ CD4+ T cells emerges coincident with a decline in the effector population." (PMID 26743592, 2016). ", antigen-specific IL6Rα+IL7R+ DP cells arises during the post-influenza-infection period." (PMID 26743592, 2016). "In the current study, we found that defective IL-7Rα signaling led to reduced accumulation of influenza-specific CD8 T cells in the secondary lymphoid organ (mdLN) at early priming stages (5 dpi) which ultimately led to reduced accumulation of influenza-specific CD8 T cells in the lungs." (PMID 34997007, 2022). "Our finding that antigen-specific effector CD4+ T cells upregulate the dual expression of IL-6Rα and IL-7R at late time points post influenza infection suggests that exposure to either cytokine could be a key determinant in further differentiation events and long-term cellular function." (PMID 26743592, 2016). "IL-7 and IL-15 are critical for memory CD8+ T-cell homeostasis 9–11, and expression of IL-7R and IL-15R by NP-specific CD8+ T cells was comparable at 2 and 6 months after influenza infection." (PMID 22965681, 2012). "This suggest that the antibody response to H. polygyrus, but not Influenza/A, is dependent on IL-7 signaling through IL-7Rα Tyr449." (PMID 24551160, 2014). "In influenza infection, a substantial number of antigen-specific DbNP366+CD8+ and DbPA224+CD8+ T cells express IL-7Rα at the peak of the acute primary response (70.2 ± 1.5 and 37.5 ± 2.4%, respectively), which does not translate into the relative numbers of T cells in the stable memory pools." (PMID 23230439, 2012). "Thus, at least for influenza in a non-TCR-transgenic B6 mouse system, the majority of the antigen-specific IL-7Rα+ CD8+ T cells do not survive into the memory phase in a non-TCR-transgenic B6 mouse system." (PMID 23230439, 2012).
psoriasis (18 papers, 2012 to 2026). An autoimmune condition characterized by red, well-delineated plaques with silvery scales that are usually on the extensor surfaces and scalp. "To investigate whether loss of IL-7Rα signaling in endothelial cells would have any impact on the progression of inflammation and on lymphatic function in chronic, psoriasis-like skin inflammation, we established imiquimod-induced skin inflammation in IL-7RαΔEC mice." (PMID 31406267, 2019). "While mIL-7-Fc exacerbated psoriasis-like inflammation, anti-IL-7Rα treatment improved edema, reduced immune cell infiltration, and decreased the cellularity of the dLN." (PMID 31406267, 2019). "In this study, we dissected the role of IL-7Rα signaling in mouse models of acute or psoriasis-like, chronic skin inflammation." (PMID 31406267, 2019). "Overall, our data describe a new role for IL-7Rα signaling in the progression of psoriasis-like skin inflammation." (PMID 31406267, 2019). "We next set out to investigate the systemic impact of IL-7Rα signaling on chronic, psoriasis-like skin inflammation." (PMID 31406267, 2019). "Here we investigated how the potentially opposing effects of IL-7Rα signaling in immune cells and in the lymphatic vasculature would affect the development and progression of psoriasis-like skin inflammation." (PMID 31406267, 2019). "Studies have suggested that IL7R is involved in the pathogenesis of psoriasis." (PMID 37373186, 2023). "A previous study demonstrated that IL-7 signaling blockade using anti-IL-7Rα monoclonal antibody (mAb) treatment or endothelial-specific deletion of IL-7Rα attenuates psoriasis-like skin inflammation mediated by infiltration of T cells and DCs into the inflamed lesion." (PMID 37373104, 2023). "In addition, studies have shown that inflammatory bowel disease is associated with increased soluble CD132 expression, and increased expression of IL-7Rα together with that of CD132 is positively related to psoriasis-like skin inflammation." (PMID 36167591, 2022). "We show for the first time that blocking IL-7Rα signaling improves psoriasis-like inflammation and might be a valuable therapeutic target." (PMID 31406267, 2019). "Next, we tested whether the anti-IL-7Rα treatment would also ameliorate inflammation in another mouse model of psoriasis." (PMID 31406267, 2019). "By contrast, when systemically enhancing or blocking IL-7Rα signaling in mice with normal IL-7Rα expression, we found that the effects on the immune compartment dominated the inflammatory response, and IL-7Rα signaling contributed to the exacerbation of psoriasis-like symptoms." (PMID 31406267, 2019). "Thus, similarly to its suggested activity in other mouse models of autoimmunity, anti-IL-7Rα treatment likely reduced the Th1 and Th17 response in the psoriasis-like skin inflammation investigated here." (PMID 31406267, 2019). "Since edema formation is one of the cardinal signs of inflammation and our previous findings had demonstrated that the IL-7/IL-7Rα axis supports lymphatic drainage, we here set out to further investigate the overall role of IL-7Rα signaling in psoriasis-like skin inflammation." (PMID 31406267, 2019). "Interestingly, the imiquimod induced psoriasis model in knocking down Tet2 mice displayed decreased skin lesions with a reduced expression of biomarkers genes, such as S100A7, IL7R, and IRF7." (PMID 34769338, 2021). "In addition, gene methylation profiles of psoriasis patients indicate that genes belonging to the IL17 signaling pathway, Staphylococcus aureus infection, interferons, and immune cells migration displayed abnormal methylation, including IRF7, IL7R, and CXCL1." (PMID 34769338, 2021). "Additionally, peripheral LECs express the two IL-7 receptor chains: IL-7Rα and the common cytokine receptor γ-chain (CD132), with endothelial-specific deletion of IL-7Rα found to result in edema and impaired lymphatic drainage in psoriasis-like skin inflammation in mice." (PMID 33923289, 2021).
prostate carcinoma (15 papers, 2007 to 2026). A carcinoma that arises from epithelial cells of the prostate gland. "Previous studies depict that high levels of IL-7 and IL-7R expression is associated with lymph node metastasis, poor survival, and poor prognosis in breast, lung, and prostate cancers." (PMID 38424167, 2024). "The gene expression profile of human prostate cancer cells from The Cancer Genome Atlas revealed that EMT pathways are strongly associated with prostate cancers that highly express both IL-7 and IL-7Rα." (PMID 31061414, 2019). "In prostate cancer, high IL-7 expression correlates with poor prognosis because IL-7R activation promotes invasion and migration via the AKT/NF-κB pathway and matrix metalloproteinase (MMP) regulation." (PMID 41596598, 2026). "In primary prostate cancer, the immune microenvironment is characterized by suppressive myeloid cells and exhausted T cells, and the expression level of IL-7/IL-7R in this microenvironment is significantly higher than that in normal tissues." (PMID 41360767, 2025). "The level of IL-7 expression has been suggested as impacting the rate of survival of patients with prostate cancer, and upregulated expression of both IL-7 and its receptor, IL-7R, have been detected in prostate tumor cells." (PMID 32585812, 2020). "Inhibition of the IL-7/IL-7R axis decreases prostate cancer cell invasion, migration, as well as MMP3 and MMP7 expression via suppressive effects on both the AKT and NFκB pathways." (PMID 32585812, 2020). "But in a solid tumor, the IL-7/IL-7R axis promoted prostate cancer cell invasion and migration by activating the AKT/NF-κB pathway and increasing MMP-3 and MMP-7 expression." (PMID 31915416, 2019). "Taken together, these results showed that IL-7 acts on prostate cancer cells expressing IL-7Rα to increase their migration and invasion." (PMID 31061414, 2019). "In this study, we modulated the expression of IL-7Rα and used inhibitors to show that IL-7 directly increases the migration and invasion of prostate cancer cells and assessed the potential of IL-7 and IL-7Rα as targets for anticancer drugs." (PMID 31061414, 2019). "This study showed that IL-7 enhances the migration and invasion of prostate cancer cells via EMT, suggesting that IL-7 and IL-7Rα are therapeutic targets for the treatment of prostate cancer." (PMID 31061414, 2019). "The IL-7/IL-7R axis has been shown to activate NF-κB in prostate cancer cells." (PMID 40240976, 2025). "The IL-7/IL-7R axis contributes to prostate cancer cell migration via the PI3K-Akt pathway." (PMID 36672342, 2023). "Moreover, IL-1β and IL-7R axis predominantly induces osteoblastic lesions and supports the skeletal colonization and metastatic progression of prostate cancer." (PMID 37127752, 2023). "Additionally, the overexpression of the interleukin-7 receptor (IL-7R) in prostate cancer cells increases the bone metastasis in a mouse model." (PMID 34064589, 2021). "This raises the hypothesis that the androgen signal can suppress the expression of IL-7Rα in AR-positive prostate cancer cells because IL-7Rα is expressed only in AR-negative prostate cancer cells." (PMID 31061414, 2019). "We thought that IL-7Rα expression may be a characteristic of advanced prostate cancer (i. e., AR-independence)." (PMID 31061414, 2019). "Interestingly, there was a statistically significant correlation between IL-7Rα and IL-7 expression in prostate cancer (r = 0.63, P < 0.001), suggesting that expression of the two molecules occurs simultaneously." (PMID 31061414, 2019). "We first explored whether prostate cancer cell line, PC-3, and its derivatives express IL-7 and IL-7Rα, and whether IL-7Rα expressed by these cells responds to IL-7." (PMID 31061414, 2019). "The IL-7/IL-7R axis is related to cell invasion and migration, and blocking the IL-7/IL-7R axis may treat prostate cancer." (PMID 28486560, 2017).
prostate carcinoma (continued). "The higher the Gleason grade in prostate cancer patients, the higher the activity of signal transducer and activator of transcription 5 (STAT5), a downstream target of IL-7 receptor (IL-7R) signaling." (PMID 31061414, 2019). "In particular, gene expression data for prostate cancer patient samples showed that expression of EMT- and stem cell-related genes was prominent in cancer cells highly expressing both IL-7 and IL-7Rα." (PMID 31061414, 2019). "In this study, we also found that DU-145 as well as PC-3 cells and its derivatives, known as androgen receptor (AR)-negative cells, express IL-7Rα, but not AR-positive prostate cancer cells such as VCaP and LNCaP-LN3 cells." (PMID 31061414, 2019). "However, bicalutamide, an AR blocker, did not increase the expression of IL-7Rα in AR-positive prostate cancer cells." (PMID 31061414, 2019).
T-cell acute lymphoblastic leukemia (15 papers, 2015 to 2025). Acute lymphoblastic leukemia of T-cell origin. "Several mutations causing activation of MAPK-ERK were discovered, notably the interleukin-7 receptor (IL-7R) pathway mutations in T-cell ALL and rat sarcoma virus (Ras) pathway mutations in precursor B-cell ALL." (PMID 35409154, 2022). "Specifically, a gain-of-function mutation in IL-7R played an oncogene role in approximately 10% of T-cell ALLs and 1% of B-cell ALLs." (PMID 34497605, 2021). "Considering this, the IL-7R mutant has been associated with T-cell acute lymphoblastic leukemia." (PMID 31379876, 2019). "IL7R is reported in childhood T-cell acute lymphoblastic leukemia, promotes cell transformation and tumor formation." (PMID 28324520, 2015).
ulcerative colitis (15 papers, 2012 to 2025). An inflammatory bowel disease involving the mucosal surface of the large intestine and rectum. "The rs10491434 SNP is a C/T variant located within the 3′UTR of the RefSeq IL7R gene, and is in high LD with the rs3194051 variant implicated in ulcerative colitis." (PMID 24911414, 2014). "The SNP is associated with ulcerative colitis and IL7R may be another example of a gene in the inflammatory response pathway demonstrating alternative polyadenylation." (PMID 23818875, 2013). "IL-17A–producing IL-7Rα+ innate lymphoid cells are potent promoters of intestinal inflammation in Tbx21−/−Rag2−/− ulcerative colitis mice." (PMID 27424033, 2016). "Here, we show that interleukin-17A (IL-17A)-producing IL-7Rα+ innate lymphoid cells (ILCs) were potent promoters of disease in Tbx21−/−Rag2−/− ulcerative colitis (TRUC) mice." (PMID 23063332, 2012). "Currently, the failure of Crohn's disease and ulcerative colitis treatment, has been reported to be closely related to the over expression of the IL‐7R signalling pathway, suggesting that IL‐7R is a fatal therapeutic target and potential biomarker for Crohn's disease and ulcerative colitis." (PMID 36802116, 2023).
lymphoma (14 papers, 2016 to 2024). A malignant (clonal) proliferation of B- lymphocytes or T- lymphocytes which involves the lymph nodes, bone marrow and/or extranodal sites. "This study was aimed to identify the clinical characteristics and single-nucleotide polymorphisms in the gene (IL7R) encoding IL-7Rα associated with thymus renewal after chemotherapy in Chinese Han individuals with lymphoma." (PMID 28082988, 2016). "IL-7R signal transduction has been shown to be associated with the prognosis of malignant lymphoma." (PMID 34497605, 2021). "In our study, we confirmed lower expression of IL7R in the lymphoma group compared to the control group." (PMID 39911484, 2024). "Compared to the control group, patients with SS had increased serum IL-7R levels and elevated IL-7 and IL-7R expression in the labial glands, and IL-7 was related to increased inflammation and lymphoma." (PMID 36389806, 2022). "Consequently, imiquimod induced a significant increase in the number of key-memory-phenotype cells and larger percentages of CD127+ (IL-7R) T cells in lymphoma, whereas imiquimod and CpG-ODN synergistically induced the growth of effector CD8+ T cells." (PMID 31508424, 2019). "Accordingly, this study focused on four specific SNPs within the IL7R locus, known to influence the IL-7Rα expression on T cells, and explored their potential contributions to the thymic regeneration after chemotherapy in adults with lymphoma." (PMID 28082988, 2016). "In comparison to lymphomas infected with ΔEBNA2 alone, the ΔEBNA2 + Myc tumors have much higher expression of IGLL1 (CD179B, surrogate light chain), DNTT (terminal deoxynucleotidyltransferase, TDT), RAG1 and IL7R." (PMID 38620028, 2024). "In order to address this question, Rag-/- mice lacking the IL-7Rα chain (Rag-/-IL-7R-/-) were reconstituted with OT-I T cells, received IL-7 therapy or PBS and were challenged with EG7 lymphoma cells." (PMID 27447484, 2016). "We found that Grail expression in patients with lymphoma CD8+ T cells and mouse CD8+ TILs negatively correlates with IL-21R expression while expression of other receptors involved in common gamma chain cytokine signalling (IL-2R, IL-7R and IL-15R) did not depend on the level of Grail." (PMID 28798332, 2017).
AIDS (13 papers, 2006 to 2025). A syndrome resulting from the acquired deficiency of cellular immunity caused by the human immunodeficiency virus (HIV). "Polymorphisms in IL7RA, the gene encoding for IL7Rα, have previously been associated with rapid progression to AIDS and with CD4+ T-cell recovery after initiation of cART, especially the missense polymorphism rs6897932." (PMID 31208153, 2019). "High IL-7 plasma levels as well as decreased membrane-associated (m)IL-7R expression of T cells were found in AIDS patients with immune failure." (PMID 28582466, 2017). "T-cell exhaustion was found in AIDS patients and was associated with decreased IL-7R expression and impaired IL-7 response." (PMID 28582466, 2017). "Signaling via the IL7R is essential for T cell homeostasis and maintenance of T cell memory, and down-regulation of IL7R correlates with depletion of CD4+ T cells and AIDS (acquired immune deficiency syndrome) progression." (PMID 17014716, 2006). "Further studies on the regulatory pathways behind bone marrow IL-7/IL-7R production and IL-7Rα-mediated signaling in HIV/AIDS patients are needed to identify the most efficacious clinical use of IL-7 in the (adjuvant) treatment of HIV-positive patients." (PMID 21209878, 2010). "We describe aberrant IL-7/soluble IL-7R expression and impaired IL-7-mediated T-cell functions in tuberculosis patients with similarities and differences to described IL-7 dysregulation seen in patients with AIDS." (PMID 28582466, 2017). "Moreover, as noted in the preceding paragraphs, unfavorable alleles of these three IL7R polymorphisms (rs6897932 C, rs987106 T, and rs3194051 A) have been related to low CD4+ T-cells and rapid AIDS progression in Caucasian naïve HIV infected patients and slower CD4+ recovery in patients on cART." (PMID 26123260, 2015). "HIV also frequently integrates into lymphocyte activation genes, such as CD5, IL7R, STAT5B, TNFAIP3, and MALT1, which are actively transcribed during immune activation, with higher integration rates in the AIDS group." (PMID 39788938, 2025). "Thus, unfavorable IL7R genotypes (rs6897932 CC, rs987106 TT, and rs3194051 AA) could lead to an increased risk of severe liver disease, by decreasing CD4+ cells count and enhancing AIDS progression in HIV/HCV coinfected patients." (PMID 26123260, 2015).